MYCN (MYCN proto-oncogene, bHLH transcription factor)
Diseases named in the same sentence as MYCN in open-access papers (continued):
Sharing a sentence is not in itself a finding about the gene and the disease.
neuroblastoma (continued). "The sensitivity of MYCN amplification to poly (ADP-ribose) polymerase 1 (PARP1) inhibition in neuroblastoma and the identification of the MYCN-PARP1/2-DNA damage repair (DDR) pathway as a driver of transition to NEPC provide the rationale for combining AURKA inhibitors with PARP1 inhibitors." (PMID 38398199, 2024). "Transgenic mouse and zebrafish models have demonstrated that MYCN is a neuroblastoma driver." (PMID 38488852, 2024). "False‐positive ALK expression also occurs in other types of tumors, such as neuroblastoma, which may be mediated by MYCN amplification." (PMID 39667359, 2024). "This study aimed to characterize the oncolytic effects of ZIKV on neuroblastoma using in vivo models, including both high-risk MYCN-amplified and non-amplified tumors." (PMID 38214542, 2024). "In neuroblastoma, elevated expression of MYCN, a member of the MYC family, can increase lipid peroxidation and promote ferroptosis, a process that may be associated with the use of GPX4 inhibitors." (PMID 39039611, 2024). "Thus, transduction of MYCN at the iPSC stage inhibited differentiation toward tNCCs, limiting the ability to model neuroblastoma." (PMID 38451815, 2024). "Similarly, structural changes, such as gene fusions and specific rearrangements, have been found to play a role in childhood cancer pathogenesis: EWSR1 in Ewing’s sarcoma, PAX3/7-FOXO in rhabdomyosarcoma, and MYCN or ALK in neuroblastoma." (PMID 38542199, 2024). "Conversely, patients with MYCN-non-amplified high-risk neuroblastoma and high TCI status have been associated with improved survival." (PMID 39099200, 2024). "Recent investigations have demonstrated that MYCN-high cancer cells exhibit heightened ferroptosis sensitivity compared with their MYCN-low counterparts, paving the way for the development of a targeted ferroptosis-inducing therapy for effectively treating MYCN-high neuroblastomas." (PMID 38428031, 2024). "Next, we wanted to study the control of TERT expression in MYCN-amplified neuroblastoma cells." (PMID 38837897, 2024). "This proposed mechanism agrees with the findings of a previous study where both AGE and SAC exhibited cytotoxic effects in SJ-N-KP human neuroblastoma cells and MYCN-amplified IMR5 cells via altered redox status and induction of mitochondrial permeability transition." (PMID 38977545, 2024). "Intriguingly, oncogenic MYCN in neuroblastoma cells also drives compensatory mechanisms to suppress ferroptosis, including induction of GSH synthesis (via GCLC) and an elevated usage of the transsulfuration pathway mediating methionine to cysteine conversion via CBS." (PMID 38908072, 2024). "Moreover, in MYCN-amplified neuroblastoma, we observed that MYCN occupies this same hypomethylated region in our MYCN-ChIP-seq analysis." (PMID 38837897, 2024). "We then evaluated whether JNJ-64619178 exhibited MYCN dependency in its effects on neuroblastoma cell viability." (PMID 38049564, 2024). "However, we note that some non–MYCN-amplified neuroblastoma cell lines are as dependent on SAGA activity as MYCN-amplified cell lines." (PMID 38820154, 2024). "We explore examples of how CYPA inhibition may be exploited to selectively kill cancers sharing characteristic genomic instability profiles, including MYCN-driven Neuroblastoma, Multiple Myeloma and Chronic Myelogenous Leukaemia." (PMID 38943005, 2024). "Among those, it is noteworthy that the P44L mutation is observed as frequently as 1.7% of high-risk neuroblastoma without MYCN amplification." (PMID 38884091, 2024). "Moreover, p300 was also found to interact with N-MYC in regulating cell proliferation in MYCN-amplified neuroblastoma cell lines." (PMID 38390324, 2024).
neuroblastoma (continued). "We examined the chromatin marks at the TERT locus and found that neuroblastoma cells with MYCN amplification and short telomeres are enriched for chromatin marks indicative of open chromatin including H3K4me3, H3K27Ac, H3K14Ac, RNA PolII, and BRD4 at the TERT promoter." (PMID 38837897, 2024). "However, TADA2B, the strongest outlier dependency in MYCN-amplified neuroblastoma, is uniquely found in the SAGA complex and is required for its KAT activity." (PMID 38820154, 2024). "Additionally, FOXO1 fusion status was predicted accurately for 97.4% of rhabdomyosarcomas and MYCN amplification was predicted with 88% accuracy in neuroblastoma." (PMID 39169157, 2024). "Approximately 50 % of poor prognosis neuroblastomas arise due to MYCN over-expression." (PMID 39313128, 2024). "MYCN tumors resembled adrenergic, while ALK/MYCN tumors resembled mesenchymal, neuroblastoma." (PMID 38451815, 2024). "MYCN reporter gene assay will be scaled up for high throughput screens of compound libraries and will aid in the future development of specific therapeutic strategies in neuroblastoma and other tumours." (PMID 39867575, 2024). "CD9 upregulation inhibits neuroblastoma metastasis, whilst also associated with favourable prognosis and lack of MYCN amplification." (PMID 38398114, 2024). "We initially performed pLHiChIP for MYCN in SH-EP-MYCN-ER neuroblastoma cells." (PMID 39177021, 2024). "Overall, subgroup 2 and subgroup 3 (to a lesser extent) were associated with poor survival in MYCN non-amplified neuroblastomas, suggesting fundamentally different mechanisms leading to an advanced disease." (PMID 38553589, 2024). "In addition, since MYCN is a well-known oncogene that plays a key role in maintaining the undifferentiated status of neuroblastoma cells 38, we also tested the effect of MYCN knockdown on CDKN3 expression." (PMID 38356706, 2024). "In addition, while human neuroblastoma cell lines can contain both mutant/amplified ALK and amplified MYCN, these tumor-derived lines also have other mutations that likely impact effects of ALK and MYCN." (PMID 38451815, 2024). "A common feature of MYCN amplified neuroblastoma cells is their high levels of ROS production." (PMID 38730615, 2024). "Interestingly, when considering MYCN amplification across the entire cohort, high CNTN1 expression was associated with a significantly increased overall survival probability for neuroblastoma patients with non-MYCN-amplified tumors." (PMID 39595172, 2024). "Similarly, zebrafish studies show that mis-expression of MYCN via the DBH promoter was sufficient to drive neuroblastoma formation." (PMID 39367051, 2024). "Thus, we focused our efforts on TADA2B to specifically interrogate the role of the SAGA complex in MYCN-amplified neuroblastoma." (PMID 38820154, 2024). "In addition, STM2457 suppressed the growth of MYCN-amplified neuroblastoma xenografts and prolonged the survival of tumor-bearing mice." (PMID 38691450, 2024). "To investigate the effect of CNTN1 on primary neuroblastoma tumor growth and metastasis in vivo, we established CNTN1 knockout (crCNTN1) using a CRISPR-Cas9 system in both the non-MYCN-amplified SK-N-AS and the MYCN-amplified SK-N-DZ high-risk human neuroblastoma cell lines." (PMID 39595172, 2024). "This study implied that these EVs might contribute to the aggressive behaviors of MYCN-amplified neuroblastoma." (PMID 38730633, 2024). "Additionally, the heatmap depicting the mRNA expression (bottom part) indicates that most neuroblastoma patients display high levels of MYCN, while the mRNA levels of EGFR, EGF, MAPK1 and CTSD are low or very low." (PMID 38611021, 2024).
neuroblastoma (continued). "As a cell line is genetically variable owing to its dispersive chromosome aberrations, we investigated whether a differential response to DNA-PKi could be observed in several MYCN-amplified neuroblastomas." (PMID 37240360, 2023). "Consistent with this, human MYCN transgene expression driven by rat tyrosine hydroxylase (TH) promoter in the transgenic TH-MYCN mice, is sufficient to recapitulate many of the features of human neuroblastoma." (PMID 37958555, 2023). "Moreover, they showed that PDZ binding kinase, a serine/threonine kinase that promotes the proliferation and self-renewal of neural stem cells, was positively correlated with LIN28B and MYCN expression in neuroblastoma cells." (PMID 37304235, 2023). "This suggests that while mitotic genes are essential for cell viability/proliferation to some degree in all neuroblastoma cells, there may be a molecular dependency on MYCN." (PMID 37958555, 2023). "For instance, MYCN amplification in high-risk neuroblastoma patients is associated with poor survival; meanwhile, non-amplified MYCN neuroblastoma with low-stage or even metastases can differentiate into benign subtypes or regress spontaneously by apoptosis." (PMID 37759629, 2023). "Furthermore, some investigators found that the inhibition of ODC1, a direct target of MYCN, inhibited neuroblastoma cell proliferation, prevented spontaneous tumourigenesis in mice, and enhanced the antitumour efficacy of conventional cytotoxicity." (PMID 37461251, 2023). "The ALK ligand, ALKAL2, has higher expression in non-MYCN- versus MYCN-amplified tumours, although it is still capable of enhancing MYCN-driven neuroblastoma even in the absence of hotspot ALK mutations." (PMID 37414143, 2023). "To determine whether AURKB, BUB1, and KIF1C are MYCN target genes, we performed ChIP-PCR and demonstrated a 4-to-10-fold enrichment of MYCN binding to the promoter regions in two MYCN-amplified neuroblastoma cell lines." (PMID 37958555, 2023). "Regardless, in neuroblastoma cell lines in which ALK is either amplified (SK-N-AS: ALK is transcriptionally controlled by MYCN) or mutated (LAN-5: ALKR1275Q), MYCN was reported to disrupt the normal cellular circadian rhythm to promote a lipogenic transcriptional program." (PMID 37414143, 2023). "In respect to MYCN, a study showed that the aggressive neuroblastoma cell line HTLA-230 bearing MYCN amplification was slightly sensitive to bortezomib (BTZ), a selective inhibitor of the proteasome, due to NRF2 activation and subsequent upregulation of the antioxidant heme oxygenase-1 (HO-1)." (PMID 37835497, 2023). "Additionally, it was shown that USP3 deubiquitinates MYCN, an oncoprotein observed in most neuroblastoma patients and considered as an indicator of tumor aggressiveness." (PMID 37170124, 2023). "•P300 regulated cell proliferation in MYCN-amplified neuroblastoma cell lines." (PMID 36708875, 2023). "This work evaluates the impact of MYCN amplification in metabolic reprogramming in neuroblastoma." (PMID 37835497, 2023). "Finally, there are pre-clinical data in neuroblastoma revealing specific MYCN-amplified neuroblastoma sensitivity to BH3 mimetics." (PMID 37189994, 2023).
neuroblastoma (continued). "This was supported by examining a tissue microarray of neuroblastoma patient samples where 64.3% of patients with MYCN amplification expressed moderate (2+) to high (3+) XIAP whereas the majority of non–MYCN-amplified patients had null to low (1+) XIAP expression." (PMID 37874199, 2023). "Furthermore, MYCN overexpression in neuroblastoma cells diminishes NKG2D ligands, impeding NK cell activation." (PMID 38087370, 2023). "The articles investigating the role of MYCN and its regulatory genes in neuroblastoma." (PMID 37274289, 2023). "Targeting MYCN overexpression to treat neuroblastoma has been challenging, and repurposing disulfiram in this context may be a game changer." (PMID 37777587, 2023). "MYCN, ALK, and PHOX2B gene mutations have been shown to increase the risk of neuroblastoma." (PMID 38001404, 2023). "Interestingly, the ISR effector ATF4 was already shown to mediate cell death upon glutamine deprivation in MYCN-amplified neuroblastoma." (PMID 37973789, 2023). "A nomogram risk model based on age, MYCN amplification and ZNF436 could predict the overall survival of neuroblastoma with higher specificity and sensitivity." (PMID 37904225, 2023). "These neuroblastoma spheroids were derived from naturally occurring mouse abdominal and thoracic neuroblastomas from transgenic mice, in which the human MYCN gene was constitutively expressed under the control of the rat tyrosine hydroxylase promoter (TH-MYCN mouse)." (PMID 37240360, 2023). "Indeed, at least one of the recently described MYCN-specific enhancer elements was recurrently detected on ecDNAs harboring MYCN in over 82.7% of neuroblastoma single cells." (PMID 37142849, 2023). "We included another high-risk neuroblastoma cell line, SK-N-SH, without 11q deletion or MYCN amplification, as a complementary model to the SK-N-AS cell line to monitor possible neuroblastoma-specific differences." (PMID 37731742, 2023). "The one adult with MYCN-amplified neuroblastoma treated at 150 mg had best response of SD." (PMID 37012551, 2023). "Moreover, loss of dihydrolipoamide S-succinyltransferase (DLST) that modulates entry of glutamine into the TCA cycle, impeded progression of MYCN-amplified neuroblastoma by impairing NADH production and OXPHOS activity." (PMID 37414143, 2023). "Neuroblastoma is a tumour in which amplification of the MYCN gene correlates with poor prognosis." (PMID 36695333, 2023). "TKIs with THZ1 synergistically induce MYCN-amplified neuroblastoma cell apoptosis." (PMID 37190100, 2023). "Our data also imply that the striking LRP8 dependency may have emerged during tumor evolution as a result of the growth advantage of MYCN‐amplified neuroblastoma displaying low expression/activity of system Xc−." (PMID 37435859, 2023). "Intriguingly, NLF, a low XIAP-expressing, MYCN-amplified neuroblastoma cell line, was responsive to all three antagonists which could be mitigated by XIAP overexpression." (PMID 37874199, 2023). "Taken together, our results support the hypothesis that ADAMTS9-AS2 regulates neuroblastoma stem-like properties and MYCN expression through LIN28B/let-7 signaling." (PMID 37991019, 2023). "Previous studies have shown that LIN28B promotes MYCN expression by interacting with pri-let-7 to inhibit let-7 maturation, and increasing N-Myc protein levels was associated with MYCN amplification, which plays a crucial role in the tumorigenesis of neuroblastoma." (PMID 37991019, 2023). "Importantly, comparative analysis of the results reciprocally confirmed our findings and highlighted the functional significance of MYCN for neuroblastoma development." (PMID 37835497, 2023).
neuroblastoma (continued). "We tested the anticancer effects of disulfiram in four neuroblastoma cell lines with MYCN amplification (IMR-32, SK-N-DZ, SJ-N-TQ-24 and IGR-N91, hereafter named N91) and two without (SK-N-AS and SK-N-SH; note that these lines do express high levels of the oncogene MYC, according to depmap.org)." (PMID 37777587, 2023). "Indeed, further analyses have revealed that GLS2 silencing substantially reduced proliferation and clonogenic potential in two MYCN-amplified neuroblastoma cell lines, Kelly and BE-2C, and attenuated their ability to form tumors in vivo." (PMID 38067269, 2023). "Age at diagnosis and MYCN amplification are critical prognostic makers of neuroblastoma." (PMID 37904225, 2023). "Moreover, AHCY inhibition reduces colony formation capacity and glutathione synthesis especially in neuroblastoma cell lines with high MYCN expression." (PMID 36870971, 2023). "Hence, BCL6 is tagged by MYCN binding, a profile that mechanistically is in line with its transcriptional upregulation in MYCN-amplified neuroblastoma cells." (PMID 37835497, 2023). "Collectively our results suggest that mitotic dysregulation is a key feature that contributes early to neuroblastoma tumor initiation and that a combination of antimitotic compounds and pro-apoptotic compounds offers synergistic therapeutic benefit in MYCN-driven neuroblastoma." (PMID 37958555, 2023). "Interestingly, in neuroblastoma, HLA-A homozygosity was detected in four out of 14 (28.6%) patients with MYCN-A tumors but only in four out of 56 (7.1%) MYCN-NA cases." (PMID 38318504, 2023). "ZNF436 had robust predictive values of MYCN amplification and overall survival of neuroblastoma." (PMID 37904225, 2023). "Rhabdomyosarcoma and neuroblastoma were stratified into known molecular subtypes: embryonal/fusion-negative (eRMS) and alveolar/fusion-positive rhabdomyosarcoma (aRMS), and neuroblastoma MYCN-non amplified (MYCN-NA), MYCN-amplified (MYCN-A), 11q wild type (11qWT), and 11q-deleted (11qLOH)." (PMID 38318504, 2023). "Furthermore, the frequency of MYCN amplification in neuroblastoma patients is around 20–30% and currently, amplification of MYCN is thought to be the best genetic characteristic to stratify high-risk NB." (PMID 37543638, 2023). "The MYCN gene is a promising target in Auger electron therapy for neuroblastoma." (PMID 38004392, 2023). "Furthermore, dPCR presents limitations, along with the divergence between tumor tissue and ctDNA, as reported here and for MYCN status in patients with neuroblastoma, 1q status and Wilms tumors and others." (PMID 37189699, 2023). "MYCN was discovered in 1983 by its tumor-driving role in neuroblastoma, a tumor of the sympathetic nervous system, and mouse models, in which tumors were initiated by amplification or forced expression of MYCN, were neuroblastoma models." (PMID 38001143, 2023). "Collectively, we presume that MYCN-mediated neuroblastoma cell proliferation may largely depend on DNA-PKcs in coordination with ATM; however, if the activation of DNA-PKcs is impaired, LIG4 could complement their repair ability." (PMID 37240360, 2023). "Our studies in the zebrafish model, therefore, support a causative role for the G-containing allele at rs2168101 in upregulating lmo1 expression levels in developing neuroblasts, which increases the rate of initiation of MYCN-driven neuroblastoma in this model." (PMID 37183825, 2023). "MYCN, a member of the myc proto-oncogene family, acts as a transcriptional factor for control of cellular differentiation and proliferation and plays an important role in the survival of neuroblastoma cells." (PMID 36831133, 2023). "Hence, we approached the mechanistic interrelationship between amplified MYCN and overexpression of metabolism-related TFs in neuroblastoma and showed that many are direct targets of MYCN in an amplification-inducible fashion." (PMID 37835497, 2023).